KMT2D (lysine methyltransferase 2D)
Diseases named in the same sentence as KMT2D in open-access papers (continued):
Sharing a sentence is not in itself a finding about the gene and the disease.
tumor (continued). "Similarly in mutations of the KMT2D gene, mutations drive the progression of tumor formation through distinct epigenetic mechanisms." (PMID 41590495, 2025). "Functional studies illustrate that loss of KDM6A or KMT2D promotes tumor growth and may sensitize cells to specific targeted therapies such as EZH2 inhibitors." (PMID 41373802, 2025). "Together, deficiency of KMT2D promotes tumor growth and sensitizes HCC to cisplatin." (PMID 39564571, 2024). "Together, KMT2D mutations promoted tumor progression by regulating FBXW7-NOTCH-MYC axis in DLBCL." (PMID 39113693, 2024). "In conclusion, mutations of histone methylation gene KMT2D may modulate tumor-induced Treg cell trafficking via the FBXW7-NOTCH-MYC/TGF-β1 axis." (PMID 39113693, 2024). "Furthermore, loss of KMT2D sensitizes HCC tumors to cisplatin with reduced tumor weight and high level of DNA damage." (PMID 39564571, 2024). "Vitamin C is able to impair tumor growth, which is compromised by deficiency of KMT2D." (PMID 39564571, 2024). "According to previous studies, KMT2D is the most commonly mutated gene in patients with newly diagnosed FL, and it was also found that KMT2D mutation acts to “accelerate the mutation” and promote invasive tumour cell subpopulation formation during FL development." (PMID 37152994, 2023). "Somatic mutations in the histone methyltransferase KMT2D are frequently implicated in tumorigenesis and depending on the biologic context, this methyltransferase may exert either tumor suppressive or promoting functions." (PMID 36292647, 2022). "Chromatin modifiers such as MLL4 (alias for KMT2D) are often mutated in Group 3 patients with MB, as already mentioned, and whether these could have a causative role in tumor formation has been tested." (PMID 35706426, 2022). "Consistent with its loss-of-function mutations, KMT2D can act as a tumor suppressor." (PMID 34194626, 2021). "Variants in KMT2D may result in abnormal enhancer regulation, which leads to changes in transcription, DNA breaks and tumor development." (PMID 33805950, 2021). "Interestingly, KMT2D-mutant tumors exhibit enhanced immune infiltration in the tumor microenvironment, and KMT2D deficiency sensitizes multiple cancer types to anti-PD1 therapy by augmenting tumor immunogenicity." (PMID 34336928, 2021). "Furthermore, KMT2D mutations were associated with low expression of KMT2D, large tumor size and unfavorable prognosis." (PMID 34336928, 2021). "Patient 13 had different exonic inactivating mutations in KMT2D in 3/5 tumor samples." (PMID 32455687, 2020). "These include the lysine methyltransferase genes KMT2C and KMT2D, which have been implicated in several other tumor types and suggests that chromatin remodeling activity may play a role in a subset of NECC." (PMID 32544169, 2020). "KMT2D encodes the protein histone-lysine N-methyltransferase 2D which is a tumor suppressor." (PMID 30176882, 2018). "Furthermore, they show that KMT2D functions as a tumor suppressor and that its loss in B cells results in diminished B cell differentiation and class switch recombination as well as lymphoma development." (PMID 26949423, 2016). "However, loss of KMT2D might be linked to tumor progression or development of therapy resistance, as observed here." (PMID 41035915, 2025). "Therefore, combining the glycolysis inhibitor 2-DG with DNA crosslinking agents or poly (ADP-ribose) polymerase (PARP) inhibitors preferentially inhibits tumor growth of KMT2D-deficient mouse HNSCC and patient-derived xenografts (PDXs) harboring KMT2D-inactivating mutations." (PMID 39117659, 2024).
tumor (continued). "Notably, one of the frequently occurring mutations of KMT2D is truncation, which leads to catalytic inactivity and loss-of-function of KMT2D, suggesting that it may function as a tumor suppressor." (PMID 39117659, 2024). "Furthermore, a conserved E2678Q mutation in the tumour suppressor and epigenetic regulator KMT2D was also identified and is predicted to be deleterious, suggesting that the CU-PC01 model may have diminished methyltransferase activity." (PMID 38667288, 2024). "However, it is unknown whether loss of KMT2C and KMT2D induces similar or unique epigenetic alterations and which underlying pathways might drive metastasis in KMT2C- or KMT2D-deficient tumours." (PMID 38926506, 2024). "Furthermore, our work revealed that CX‐5461, a specific RNA polymerase I inhibitor, could effectively reduce tumor burden and significantly prolong the survival of mice bearing Kmt2d‐deficient AML." (PMID 37142882, 2023). "Additionally, KMT2D deficiency attenuates cancer cell migration, promoting tumor growth." (PMID 33805950, 2021). "This may imply that KMT2C and KMT2D proteins exert coordinated and synergistic functions in enhancer elements and their loss during carcinogenesis deregulates cell adhesion and signaling with profound effects to tumor progression and invasion." (PMID 30665945, 2019). "Recurrent mutations in key epigenetic regulators such as EZH2, KMT2D, CREBBP, and TET2 lead to altered chromatin states, repression of tumor suppressor genes, and enhanced oncogenic signaling." (PMID 40943058, 2025). "Tumor volume and weight were slightly reduced by CM treatment, which was enhanced by KMT2D overexpression, and the anti-cancer effect was abolished by ITGAL deficiency." (PMID 40718439, 2025). "RICTOR, a core component of the oncogenic mTOR2 complex, was altered in 21% of tumours, as was the tumour suppressor gene KMT2D." (PMID 41015991, 2025). "Growth signaling aberrations, epigenetic dysregulation, and disruption of cell fate determination define the somatic mutational profile of our patient's tumor, which includes mutations in PIK3R1, KMT2D, and NOTCH1." (PMID 40124187, 2025). "Loss-of-function mutations in KMT2D, which encodes an H3K4 methyltransferase, diminish enhancer activity and repress differentiation-related genes, thereby maintaining tumor cells in an undifferentiated state." (PMID 41383509, 2025). "In terms of tumor suppressors, KMT2D is an epigenetic regulator required for monomethylation of H3K4 at distal regulatory enhancers." (PMID 39455281, 2025). "Enhance the stability of the WDR5 protein, promote the synthesis of the KMT2D‐enzyme complex and stimulate tumour growth." (PMID 40211955, 2025). "In parallel, frequent mutations in chromatin modifiers (e.g., KDM6A, KMT2D) and overexpression of histone-modifying enzymes (e.g., EZH2) alter the tumor epigenome to promote immune evasion and tumor aggressiveness." (PMID 40918525, 2025). "Additional driver alterations are necessary for the appearance of a tumor and 90% of patients with FL have certain mutations in genes regulating transcription and chromatin remodeling such as CREBBP, EP300, KMT2D and EZH2." (PMID 40725159, 2025). "A KMT2D deficiency leads to reduced phosphoinositide-3-kinase-interacting protein 1 expression and increased phosphorylated AKT, accelerating tumor growth in NSCLC by activating the PI3K/AKT pathway and upregulating SOX2 expression." (PMID 39544292, 2024). "Endothelial cells from Kmt2c KO and Kmt2d KO tumours were distinct from the WT and shared top upregulated genes, including Cd74, Cxcl9, H2-Ab1 and H2-Eb2." (PMID 38926506, 2024).
tumor (continued). "In the colon, binding of FOXD2 to compacted chromatin facilitates recruitment of KMT2D and rewiring enhancer through deposition of H3K4me1, which functions as a tumor suppressor." (PMID 39117610, 2024). "The tumor suppressor KMT2D, which incorporates into a large multiprotein complex of the COMPASS family, catalyzes the methylation of lysine 4 in histone 3, and thus regulates the expression of genes in an epigenetic manner." (PMID 38786098, 2024). "In regard to the physiological role of KMT2D in HCC, deficiency of KMT2D substantially improves cell viability of HCC cell, providing the evidence that KMT2D exerts a tumor-suppressive role in HCC cells." (PMID 39564571, 2024). "Specifically, modifiers like KDM2A have an oncogenic effect on many cancers, whereas others such as SETD2 and KMT2D play tumor suppressive roles." (PMID 39765675, 2024). "Rather unexpectedly, KMT2D has divergent functions in different types of cancers and can act as a tumor suppressor or an oncogene." (PMID 39117659, 2024). "Tumour specific variants in CDKN2A, NOTCH1 and KMT2D present at baseline were detected longitudinally in ctDNA and increased in frequency at recurrence." (PMID 38846976, 2024). "Physiologically, KMT2D was identified as a tumor suppressor and mediates the antitumor effect of vitamin C in HCC." (PMID 39564571, 2024). "Taken together, these results suggest that KMT2D functions as an important tumor suppressor in HNSCC and Kmt2d deficiency significantly promotes not only HNSCC initiation, but also HNSCC progression and metastasis." (PMID 39117659, 2024). "This indicates that KMT2D offers protective effects for patients with MB and emphasizes its role as a tumor suppressor." (PMID 39765675, 2024). "Upregulation of programmed death ligand 1 was also confirmed by immunofluorescence in both Kmt2c KO and Kmt2d KO primary tumours." (PMID 38926506, 2024). "Analyses of the RNA-seq data showed increases in genes linked to tumor growth in the KMT2B and KMT2D KD BCCs." (PMID 38347590, 2024). "In contrast to KMT2A and KMT2B, KMT2C and KMT2D inhibit cell proliferation and are often considered tumor suppressors in different types of cancer." (PMID 38791111, 2024). "Using the tumour suppressor gene KMT2D as an example for our framework, we performed in silico genetic network analyses to gain further insights into its functions and identify its cancer type-specific genetic interactors." (PMID 39578878, 2024). "Inhibition of KMT2D with current treatments such as PI3K inhibitors reduced tumor volume in ER-positive BC." (PMID 38347590, 2024). "The truncated proteins generated from nonsense, deletion and splice site mutations lack the C-terminal SET domain needed for enzymatic activation, indicating that KMT2D is a tumor suppressor." (PMID 38609996, 2024). "KMT2D serves as an oncogene, promoting tumor growth and metastasis; however, it also has functions regarding radioresistance." (PMID 37455903, 2023). "Recently, various new fusion partners of BCOR have been documented, such as MAML3, ZC3H7B, RGAG1, and KMT2D, further increasing the complexity of such tumor entities, although the molecular pathogenetic mechanism remains to be elucidated." (PMID 36765856, 2023). "These four 5′-tRFs tumor subtypes also showed significantly different frequencies of recurrent mutations in driver genes such as FOXA1 and KMT2D, with tF-2 having the highest frequency." (PMID 36661724, 2023). "As a tumor suppressor gene, KMT2D is known to activate Bcl6 and Sirt1 in addition to Per2, resulting in inhibitory effects on Notch and K-Ras pathways." (PMID 36841815, 2023).
tumor (continued). "KMT2D plays contradictory roles in different types of malignancies, some studies stated it has pro-tumorigenic functions, whereas others reported tumor-suppressive characteristics." (PMID 36841815, 2023). "Based on these observations, we set out to examine the impact of combined CREBBP and KMT2D haploinsufficiency in vivo and explored how these two tumor suppressors functionally interact in normal and malignant GC B cells to promote oncogenesis." (PMID 36893259, 2023). "Seven heterozygous protein-truncating mutations were found in tumor suppressor genes including RB1, FBXO11, FAT1, KMT2D, KMD6A, ACVR2A and ZFHX3." (PMID 36702998, 2023). "UTX (KDM6A), MLL3 (KMT2C), and MLL4 (KMT2D), the core catalytic components of the COMPASS-like complex, are all considered tumor suppressors, with frequent loss-of-function genomic alterations found in a broad spectrum of human cancers." (PMID 37261974, 2023). "Studies have shown that epigenetic-related gene mutations can lead to increased TMB in tumor cells, such as ARID1A and KMT2D." (PMID 36479108, 2022). "Collectively, these results demonstrated that the expression of KMT2D is essential for OSCC tumor growth in vivo." (PMID 35477537, 2022). "Given the role of KMT2D in tumor promotion and suppression, however, the mechanisms by which KMT2D affects the development of patients with OSCC remain exceedingly unclear." (PMID 35477537, 2022). "In the WES samples, we detected somatic mutations in known PCa genes, including KMT2D, MTOR, SPOP, and PIK3R1, indicating tumor content in tissues assessed by single-cell analysis." (PMID 35013146, 2022). "Here, we found that the expression of KMT2D was elevated in OSCC specimens compared to adjacent tissues and, more importantly, was associated with increased tumor grade." (PMID 35477537, 2022). "The BAF complexes/SMARCB1, Menin, and KMT2D all share additional roles in their inhibition of canonical Wnt signaling, thereby acting in a tumor-suppressive manner." (PMID 36969744, 2022). "As a result, we found that the upregulation of KMT2D not only correlated with a more advanced pathologic tumor grade but also contributed to aggressive cancer cell behaviors, providing a novel rationale for targeting KMT2D function in patients with OSCC." (PMID 35477537, 2022). "KMT2D encodes a conserved protein of the SET1 family of histone lysine methyltransferases and is a tumor-suppressor in ESCC." (PMID 36741715, 2022). "In such cases, KMT2D deficiency can attenuate the proliferation of affected cell lines or the growth of PDX tumors, even if KMT2D is a tumor suppressor." (PMID 34194626, 2021). "It is possible that KMT2D-mediated methylation alters the functions of certain oncogenic factors or tumor suppressors to regulate tumorigenesis." (PMID 34194626, 2021). "The kinases AKT and SGK1 interact with and phosphorylate KMT2D to reduce its methyltransferase activity, which is important for ER’s tumor-promoting function in ER-positive breast cancer cell lines." (PMID 34194626, 2021). "Subsequently, we systematically explored the mechanism whereby KMT2D LCDs regulate the expression of H3K4me1 and transcription factors related to tumor proliferation and metastasis." (PMID 34758724, 2021). "Mechanistically, KMT2D was found to upregulate the circadian rhythm repressor PER2 which plays an important role in tumor suppression." (PMID 35071240, 2021).
tumor (continued). "One possibility is that tissue-specific transcription factors direct the KMT2D complex to a unique set of tumor-promoting genes or tumor suppressor genes in a tissue-dependent manner." (PMID 34194626, 2021). "KMT2D mutations are mainly truncating events, with few missense mutations in the SET domain, which all impair its enzymatic function, indicating that KMT2D acts as tumor suppressor gene in B cells." (PMID 34456919, 2021). "In contrast to its tumor-suppressive function, KMT2D appears to activate tumor-promoting pathways in certain contexts or tissue-specific manners." (PMID 34194626, 2021). "We identified nonsynonymous SNVs in tumor tissues, such as SMARCA4 (in 192D0360T and 192D0641T), BCOR and LRP1B in 192D0641T, as well as frameshift mutations of KMT2D in 192D0695T and truncating mutations of PTCH1 in 192D0583T." (PMID 33707557, 2021). "Another critical question is how KMT2D can act as a tumor suppressor or a pro-tumorigenic factor in a tissue-dependent manner." (PMID 34194626, 2021). "Our results reveal that LCDs in the KMT2D protein play an essential role in tumor survival by promoting tumor cell proliferation and inhibiting tumor cell apoptosis." (PMID 34758724, 2021). "In support of KMT2D’s role as a tumor suppressor in cSCC, inhibition of the histone demethylase enzyme that opposes KMT2D’s function, LSD1 (KDM1A), has been shown to both promote epidermal differentiation and suppress cSCC in 3D human cSCC organoids." (PMID 34298617, 2021). "KMT2D is a known cancer-related protein that regulates tumor growth and metastasis, thus influences prognosis." (PMID 32239176, 2020). "The mutation allele frequencies of ATM and JAK3 were significantly correlated with the disease stage, and mutated KMT2D, ASXL3 and JAK3 were positively correlated with the metabolic tumor burden of the patients." (PMID 32695399, 2020). "The study showed that KMT2D was responsible for establishing super-enhancers and broad H3K4me3 peaks at tumor-suppressor genes, such as Dnmt3a and Bcl6, and activating their expression." (PMID 33302406, 2020). "KMT2D is mutated in FL and DLBCL, where it functions as a tumour suppressor, promoting lymphomagenesis in murine models." (PMID 31320741, 2019). "KMT2D plays a critical role in regulating development, differentiation, metabolism, and tumor suppression." (PMID 31470906, 2019). "Many commonly mutated large tumour suppressor genes (e.g. KDM6A, KMT2D) with SMs widely distributed across the gene were unsuitable for inclusion." (PMID 31077629, 2019). "Our previous study, together with others, demonstrated that KMT2C and KMT2D function as tumor suppressors." (PMID 28055972, 2017). "The apparent loss-of-function alterations, including frameshift and nonsense mutations, suggest a tumor suppressor role for KMT2C and KMT2D." (PMID 24240169, 2013). "However, under 3D culture, Kmt2d gRNAs were remarkably enriched, which supports the tumor suppressor role of KMT2D." (PMID 38853928, 2025). "Notably, most of these genes (Kmt2d, Bcor, Smad, Nf2, Lats1) are tumor suppressors in human cancers." (PMID 38853928, 2025). "Additionally, studies have identified KMT2D as a tumour suppressor, specifically in follicular lymphoma and diffuse large B-cell lymphoma." (PMID 41341998, 2025). "The functional impact of KMT2D has been diverse from hepatic circadian rhythm to tumour suppressor." (PMID 41341998, 2025). "In summary, our study demonstrates that KMT2D functions as a tumor suppressor in HNSCC." (PMID 39117659, 2024).